APOL1 (apolipoprotein L1)
Diseases named in the same sentence as APOL1 in open-access papers (continued):
Sharing a sentence is not in itself a finding about the gene and the disease.
glomerulosclerosis (20 papers, 2012 to 2025). A hardening of the kidney glomerulus caused by scarring of the blood vessels. "Freedman reported the significance of APOL1‐associated glomerulosclerosis as a distinct clinical entity characterized by solidification rather than obsolescence in arteriolar nephrosclerosis." (PMID 39379463, 2024). "APOL1 affects endosomal trafficking, inflammasome activation and autophagic flux and can promote podocyte loss and glomerulosclerosis." (PMID 31390993, 2019). "In contrast to MYH9, APOL1 can explain why the alleles proposed to cause glomerulosclerosis are found at such high frequency in the African-American population." (PMID 23300552, 2012). "First, the magnitude of the effect of APOL1 G1 and G2 on the risk of glomerulosclerosis is sufficiently unusual that these alleles were proposed to occupy a unique niche in human disease." (PMID 23300552, 2012). "This individual and his family offer a unique opportunity to test causality between APOL1 null alleles and glomerulosclerosis." (PMID 23300552, 2012). "Both groups found that African-American glomerulosclerosis correlates more strongly with the G1 and G2 alleles of APOL1, which lies immediately centromeric to MYH9." (PMID 23300552, 2012). "This complicates the comparison of findings between mice expressing APOL1 with different polymorphisms, particularly because the higher APOL1 concentrations in Alb/APOL1-G1 mice were associated with the higher levels of glomerulosclerosis, tubular injury, and albuminuria, as well as reduced eGFR." (PMID 36279295, 2022). "However, doxycycline-induced renal risk-APOL1 over-expression in podocytes caused severe podocyte damage, glomerulosclerosis, and resulted in enhanced expression of CXC chemokines in the kidney, similar to that reported in the NEPTUNE clinical study." (PMID 32854642, 2020). "Therefore, if an APOL1 canonical loss of function mutation (a null allele) predisposes to glomerulosclerosis, then APOL1 loss of function is the likely mechanism of glomerulosclerosis in individuals with African-ancestral G1 and G2 alleles." (PMID 23300552, 2012). "Interestingly, it has been shown that APOL1 may cause toxic renal effects through programmed cell death pathways leading to glomerulosclerosis." (PMID 26147622, 2015). "Prior to investing significant effort into screening asymptomatic individuals for APOL1 G1 and G2 alleles, and looking for gene-environment interactions with APOL1, we suggest that additional effort focus on definitively establishing causation of glomerulosclerosis." (PMID 23300552, 2012). "Apolipoprotein L1 (APOL1), the best-known gene, imparts a greatly increased risk of adult-onset FSGS and is associated with lower kidney function, more glomerulosclerosis and interstitial fibrosis, and greater propensity to progress to ESRD." (PMID 40236664, 2025). "Histopathological analysis of the IFN-γ-treated APOL1-transgenic mice revealed that G1/G1 and G2/G2 mice also developed glomerulosclerosis, with characteristics similar to those seen in humans." (PMID 34350953, 2021). "Based on these and other data, APOL1 supplanted MYH9 as the candidate disease gene for glomerulosclerosis and hypertensive nephrosclerosis among African-Americans." (PMID 23300552, 2012). "For this reason, we feel it is necessary to examine the strengths and weaknesses of APOL1 as a candidate gene for African-American glomerulosclerosis with an extended introduction in order to justify the aims of our study." (PMID 23300552, 2012). "This latter idea forms the basis of the prevailing hypothesis for the G1 and G2 alleles: that APOL1 is expressed within podocytes, that the G1 and G2 alleles inappropriately activate autophagy within podocytes, and that the resulting death of podocytes results in glomerulosclerosis." (PMID 23300552, 2012). "For instance, apolipoprotein L1 (APOL1) gene renal-risk variants are strongly associated with nondiabetic glomerulosclerosis and all cases of ESRD in African Americans." (PMID 39379463, 2024).
glomerulosclerosis (continued). "Together with our analyses in vitro, these results may suggest a widespread involvement of pyroptotic angiopathy concurrent with APOL1 upregulation, possibly contributing to a synergistic feedforward effect of glomerular sclerosis and collapse." (PMID 38838223, 2024). "For the sake of argument, assuming a higher phenotypic penetrance of 50% glomerulosclerosis with null alleles, then we would require the absence of glomerulosclerosis in 6 APOL1 null people to show significance by Chi-square analysis (two tailed p = 0.0455)." (PMID 23300552, 2012). "Based on measurements of blood pressure, BUN, creatinine, albuminuria, genotyping and immunoblotting, this APOL1 null individual does not have glomerulosclerosis, nor do his relatives who carry APOL1 null alleles." (PMID 23300552, 2012). "We show that APOL1 BAC transgenic mice homozygous for the risk variants G1 and G2, but not G0, develop overt kidney disease in response to IFN-γ, which is characterized by high albuminuria, increased serum creatinine and BUN, glomerulosclerosis and podocyte loss, and eventual death." (PMID 34350953, 2021). "Secondly, assuming that APOL1is the relevant disease gene, there are no data on the mechanism by which the G1 and G2 alleles of APOL1 (and not the wild type allele) might cause glomerulosclerosis." (PMID 23300552, 2012). "These two APOL1 transgenic mouse lines did not manifest albuminuria or glomerulosclerosis during the course of the study." (PMID 30417125, 2018). "Surprisingly, an APOL1 null individual from a small rural village in central India does not have glomerulosclerosis." (PMID 27138898, 2016). "However, if this individual does not have glomerulosclerosis this would support (but would not prove) an alternative hypothesis: that the cause of kidney disease is not due to recessive inheritance of APOL1 G1 and G2 themselves, but rather something that is linked to APOL1 G1/G2." (PMID 23300552, 2012). "However, APOL1 may not be the gene responsible for African-American glomerulosclerosis at this locus on Chr22." (PMID 23300552, 2012).
lupus nephritis (19 papers, 2013 to 2025). Glomerulonephritis in the context of systemic lupus erythematosus. "APOL1 risk alleles were previously associated with ESRD in lupus nephritis patients of African descent, while MYH9 is more relevant in European ancestry populations." (PMID 39857298, 2025). "The role of immune activation in AMKD has been seen in HIV-associated nephropathy, lupus nephritis, and COVID-19-associated nephropathy, highlighting the potential impact of immune cell function dysregulated by risk-variant forms of APOL1." (PMID 40501951, 2025). "In this study, we evaluated the role of MYH9 and APOL1 gene polymorphisms in the risk of CKD in Brazilian patients with lupus nephritis (LN)." (PMID 24658608, 2014). "For example, genetic variants in genes expressed in the kidney (including TNFRSF1B, KLK1, KLK3, ACE, AGT, and APOL1) may result in increased susceptibility to kidney injury and, as a result, in progression to lupus nephritis." (PMID 39124752, 2024). "The results were maintained after adjusting for the different ancestry covariates, indicating that in this cohort, MYH9, but not APOL1, gene polymorphisms confer an increased risk of CKD in lupus nephritis patients, independently of race." (PMID 39857298, 2025). "Variants of apolipoprotein L1 gene (APOL1) are associated with progressive nondiabetic nephropathy, cardiovascular disease, as well as immune-associated renal diseases, including lupus nephritis." (PMID 35159216, 2022). "CMA in the APOL1 mediated nephropathy has not been pursued yet, although activated macroautophagy has been reported in lupus mice and patients with lupus nephritis." (PMID 35159216, 2022). "APOL1 genotyping could be helpful and clinical testing is recommended in different clinical conditions, such as kidney transplant patients, living donors, HIV-infected patients, FSGS, lupus nephritis, and interferon treatment candidates." (PMID 36588788, 2022).
pancreatic cancer (16 papers, 2020 to 2025). "In vitro, the inhibition of APOL1 significantly reduced cell growth and caused cell cycle arrest and apoptosis, while also decreasing cell proliferation in vivo, as demonstrated by the smaller tumor size in a pancreatic cancer mouse model." (PMID 38067270, 2023). "APOL1 (apolipoprotein L1), an apolipoprotein family member, has been proven to influence tumor proliferation and metastasis in clear cell renal cell carcinoma and pancreatic cancer." (PMID 40649778, 2025). "In pancreatic cancer, APOL1 was found to promote inhibit apoptosis and cell proliferation via the regulation of NOTCH1 signaling, confirming its role as an oncogene." (PMID 40649778, 2025). "In pancreatic cancer, APOL1 is known to promote proliferation and inhibit apoptosis; however, in renal cell carcinoma, it does not alter proliferation and instead inhibit cell migration and invasion." (PMID 38680858, 2024). "Studies have confirmed that APOL1 promotes the proliferation and invasion of pancreatic cancer cells by activating the NOTCH1 signaling pathway." (PMID 38410113, 2024). "Given that this study was performed on mouse models, further research using human cells is required to investigate the effects of APOL1 in the pathogenesis of pancreatic cancer and to address its potential as a biomarker." (PMID 38067270, 2023). "The expression levels of BAK1, ITGA3, BAG3, and APOL1 were statistically increased in pancreatic cancer samples versus normal samples, while those of RAB24 was decreased." (PMID 35488119, 2022). "BAK1, ITGA3, BAG3 and APOL1 were highly expressed in most pancreatic cancer and pancreatic ductal adenocarcinoma cell lines, while RAB24 was poorly expressed." (PMID 35488119, 2022). "Using univariate Cox regression, a forest map was generated showing seven ARGs associated with pancreatic cancer prognosis: BAK1, ITGA3, BIRC5, WDR45, BAG3, APOL1, and RAB24." (PMID 35488119, 2022). "We identified APOL1 was abnormally elevated in human pancreatic cancer tissues compared with that in adjacent tissues and was associated with poor prognosis." (PMID 34341330, 2021). "The results showed that knockdown of APOL1 significantly inhibited the proliferation and promoted apoptosis of pancreatic cancer." (PMID 34341330, 2021). "The expression of APOL1 was prevalently upregulated in several cancers, including head and neck squamous cell carcinoma 58, papillary thyroid carcinoma 59, small cell lung carcinoma 60, hepatocellular carcinoma 61, pancreatic cancer 57, and bladder cancer." (PMID 39309431, 2024). "APOL1 is also known to play a role as an oncogene in pancreatic cancer." (PMID 38680858, 2024). "APOL1 appears to play a complex dual role in the development and progression of pancreatic cancer." (PMID 38067270, 2023). "Nevertheless, the role of APOL1 in the regulatory mechanisms of pancreatic cancer remains unknown and should be explored." (PMID 34341330, 2021). "APOL1 was found to be overexpressed in pancreatic cancer, lung adenocarcinoma and papillary thyroid carcinomas compared to matched normal tissues, and it was found to have prognostic value for pancreatic cancer and lung adenocarcinoma." (PMID 33587010, 2021). "In addition to that, there is controversy about whether APOL1 is upregulated or downregulated in pancreatic cancer, and more research is needed." (PMID 38067270, 2023). "Consistently, ITIH3, which has significant involvement in extracellular matrix remodeling during tumor progression, along with APOA1, APOE, APOL1, and CA19-9, constitutes a biomarker panel for pancreatic cancer." (PMID 37628784, 2023). "Using advanced mass spectrometry-based techniques, it was shown that using a panel of APOA1, APOE, APOL1, and trypsin inhibitor heavy chain H3 (ITIH3) can provide a sensitivity of 95% and specificity of 94.1% in the diagnosis of pancreatic cancer." (PMID 38067270, 2023). "Moreover, a recent study demonstrated that APOL1 could predict the prognosis of pancreatic cancer." (PMID 34809598, 2021).
pancreatic cancer (continued). "It has been demonstrated that APOL1 may function as an oncogene to stimulate proliferation and block apoptosis by triggering the expression of the NOTCH1 signaling pathway in pancreatic cancer." (PMID 39091293, 2024). "Therefore, the ability of APOL1 to activate NOTCH1 signaling is thought to play a critical role in regulating cell proliferation and apoptosis in pancreatic cancer cells." (PMID 38067270, 2023). "The three genes, COL12A1 APOL1 and MMP14, may be vital in mediating the progression of pancreatic cancer." (PMID 33027767, 2020). "Compared with those from the normal controls, immunohistochemical results from the pancreatic tissues revealed statistical increases in the expression of BAK1, ITGA3, BAG3, and APOL1 in pancreatic cancer patients; no immunohistochemical data were available for RAB24." (PMID 35488119, 2022). "In summary, APOL1 could function as an oncogene to promote proliferation and inhibit apoptosis through activating NOTCH1 signaling pathway expression in pancreatic cancer; therefore, it may act as a novel therapeutic target for pancreatic cancer." (PMID 34341330, 2021).
sickle cell disease (16 papers, 2015 to 2026). Sickle cell anemias are chronic hemolytic diseases that may induce three types of acute accidents: severe anemia, severe bacterial infections, and ischemic vasoocclusive accidents (VOA) caused by sickle-shaped red blood cells obstructing small blood vessels and capillaries. "To evaluate whether known variants with ancestral divergence are replicated in the All of Us cohort, we examined the frequency of the rs334 mutation in HBB, known to be associated with sickle cell disease, and the APOL1 G1 and G2 alleles." (PMID 38374434, 2024). "The next step could be to define novel actionable genes and variants that are relevant to Africa, e.g., sickle cell disease or APOL1 variants." (PMID 31293624, 2019). "Over time, there has been an extension in the spectrum of APOL1-associated kidney diseases, including systemic lupus erythematosus, membranous nephropathy, sickle cell disease, and even an association of two risk variants of APOL1 in diabetic patients with CKD." (PMID 29903699, 2018). "In a zebrafish model hypoxia evoked suppression of both the MYH9 and APOL1 genes and the similar nephrogenic effect was induced, while in sickle cell anemia mouse model increased kidney cortex MYH9 expression was found." (PMID 32873246, 2020). "Pathogenic genotypes were relatively common: APOL1-mediated kidney disease (MIM:612551; n = 2,233), G6PD deficiency (MIM:305900; n = 1,549 including 248 homozygous females), hATTR (MIM:105210; n = 1,108) and sickle cell disease (SCD (MIM:603903; n = 240)." (PMID 41282679, 2025). "Previous studies demonstrate that, in conjunction with HIF involvement in kidney diseases, hypoxic insults, such as those observed in disease-induced acute kidney injury (AKI) or sickle cell disease, drive the progression of kidney disease by promoting an increase in APOL1 expression." (PMID 41010023, 2025).
trypanosomiasis (16 papers, 2012 to 2025). Infection with protozoa of the genus trypanosoma. "Selection pressures have increased the frequencies of APOL1 kidney risk variants and HbS due to their protective properties in areas of Africa where trypanosomiasis and malaria are endemic." (PMID 38812969, 2024). "A single variant APOL1 allele is sufficient to protect against trypanosomiasis however, risk for kidney disease is recessive requiring two variant alleles." (PMID 31661509, 2019). "In reference to the first open question, genetic discoveries have clearly established that variant alleles of APOL1 were positively selected in Africa because they conferred resistance to trypanosomiasis." (PMID 24949636, 2014). "In this case-control study, we test the prevailing hypothesis that these APOL1 variants reduce trypanosomiasis susceptibility, resulting in their positive selection in sub-Saharan Africa." (PMID 28537557, 2017). "No APOL1 risk alleles were found in the 88 patients of the cohort, likely because of an absence of selection pressure from Trypanosomiasis in Oceania." (PMID 40630292, 2025). "As a secreted protein, APOL1 can induce lysosomal membrane depolarization and a continuous chloride influx, representing the mechanism by which APOL1 promotes lysis of trypanosomes and imparts resistance to trypanosomiasis." (PMID 33433692, 2021).